IL6 (interleukin 6)
Diseases named in the same sentence as IL6 in open-access papers (continued):
Sharing a sentence is not in itself a finding about the gene and the disease.
infection (continued). "Thus, IL6 gene expression correlates with severity of the infection in ducks." (PMID 30634569, 2019). "Additionally, microRNAs induced at 56 dayspost-infection may act to reduce damage to lung tissues; for example themiRNA-26b-5p, which negatively regulates the expression of IL-6, could influence theamount of T cells at 56 days post- infection." (PMID 30776047, 2019). "Furthermore, the NMB/NMBR system appeared to increase IFN-α expression and decrease IL-6 expression after PR8 infection, which may serve to establish an antiviral state in the host." (PMID 31601264, 2019). "Collectively, this evidence suggests that unknown activities of live pathogen infection regulate myeloid differentiation involving an IL-6R-mediated process and implies cross-talking of regulatory pathways between live Mtb, IL-6 and IFN signaling to boost myeloid differentiation of CD34+ cells." (PMID 31637998, 2019). "However, whether the NDV strains have devised similar strategies to interfere with the production of IFN‐γ and IL‐6 at the time point of infection needed to be further elucidated." (PMID 30070070, 2019). "However, for some infections, the expression of IL-6 is reduced." (PMID 31998294, 2019). "Our studies showed that miR‐223Y/− neutrophils were hyperactivated and because they expressed IL‐6, which was important for S. aureus clearance in a subcutaneous infection model using Il6−/− mice, we investigated whether miR‐223Y/− neutrophils preferentially kill bacteria at wound sites." (PMID 30171089, 2018). "Therefore, high secretion of IL-6 by mycobacteria-infected MDSCs could represent a positive feedback for maintenance and recruitment of MDSCs at the site of infection." (PMID 30405617, 2018). "Infection of ZIKV progressively damaged mouse testes, increased testicular oxidative stress as indicated by the levels of reactive oxygen species, nitric oxide, glutathione peroxidase 4, spermatogenesis-associated-18 homolog in sperm and pro-inflammatory cytokines including IL-1β, IL-6, and G-CSF." (PMID 29447264, 2018). "In summary, our data demonstrate that S473 phosphorylation is functionally linked to increased expression of IFN-β, IL-6, and IL-8 and support our hypothesis, that phosphorylation at S473 modulates the corepressor activity of TRIM28 during infection with HPAIV." (PMID 30323812, 2018). "Cytokines, such as TNF, IFN-γ, IL-6 and IL-1β, are likely to be beneficial in the early stages of the infection in parasite clearance, but might actually contribute to the pathogenesis associated with CM, and to disease severity and death if produced in an unregulated manner." (PMID 30477519, 2018). "Hence, increased production of PGE2 in macrophages that had contact with EV Y supports reduced production of pro-inflammatory cytokines (TNF-α) and NO that occurred in plasma and spleen-cell supernatants (TNF-α and IL-6) from mice inoculated with EV Y before infection." (PMID 29755471, 2018). "In chickens, activated macrophages produce a variety of pro-inflammatory cytokines, and modulation of the inflammatory reaction via the upregulation of a few inflammatory cytokines (IL-1β, IL-6, IL-8, and IL-18) might contribute to bursa lesions after vvIBDV infection." (PMID 28086922, 2017). "Additionally, 46 genes encoding for secreted proteins may serve as markers in blood for the degree of protection (Cxcl9, Gp2, and Pla2g2d), intensity of infection (Retnla, Saa3, Il6, and Il1b), or adaptive recall responses (Ighg, C1qb)." (PMID 28243609, 2017). "Thus we asked whether differential IL-6 activity could explain the different outcomes observed during reactivation and primary infection." (PMID 28400599, 2017). "More importantly, by comparing infected IL-6−/− and wild-type mice and by depleting IL-6 in infected wild-type mice using a neutralizing monoclonal antibody, we uncover that endogenous IL-6 functions to protect mice from EV-A71 infection and reduce tissue viral loads." (PMID 29233145, 2017).
infection (continued). "Addition of either IL-6 or soluble IL-6 receptor to uninfected monocytes was not sufficient to pheno-copy the effect of LPS on monocyte susceptibility to lytic IE gene expression upon infection." (PMID 28400599, 2017). "An increase in IL-17A gene expression following infection is particularly interesting since cell signaling mediated by this cytokine plays a key role in regulating the expression of other inflammatory mediators, such as IL-6, via a mechanism that involves NF-κB-mediated transcription." (PMID 28202084, 2017). "Moreover, we found that IL-6 is important to the protective response during the infection." (PMID 28871251, 2017). "While indisputably the most dominating cytokine induced by infection in this model system, a diversity of additional expressed and modulating cytokines like IL-6, IL-12, MCP-1, IFN-β, IFN-γ and IL-10 may also contribute to the therapeutic outcome with bacteria." (PMID 28445131, 2017). "However, IL-6 and TNF-α expression in infected wild-type DCs decreased significantly with DenV2 infection, in comparison with infected TLR2-deficient DCs (227 ± 16 vs. 178 ± 11 for IL-6 MFI in BL/6 and TLR2 KO; 259 ± 9 vs. 218 ± 11 for TNF-α MFI in BL/6 and TLR2 KO)." (PMID 29285314, 2017). "Furthermore, IL-6 is massively expressed after super-infection in in vitro and in vivo models." (PMID 28195157, 2017). "In addition, the high bacterial burden present in our system may lead to an overwhelming cytokine signal, as demonstrated by the very high levels of the key L. monocytogenes cytokine IL-6 observed in response to infection, which may hide potential differences." (PMID 28589100, 2017). "However, following infection, IL-6 activates the release of CRP14." (PMID 28473693, 2017). "After the infection of untransfected and hBD-2- or hBD-3-transfected Caco-2 cells with E. faecium and/or S. typhimurium, we examined the host response by evaluating the expression of proinflammatory cytokines IL-6, IL-8 Il-1α, and IL-1β and anti-inflammatory cytokine TGF-β by real-time PCR." (PMID 29250559, 2017). "Therefore, the increase of IL-6 precedes that of CRP after infection; thus, IL-6 may be a more sensitive marker for PJI." (PMID 28473693, 2017). "In addition 5 out of 20 anti-IL-6 treated mice had to be euthanized at day 11 p.i. as they had reached the study’s humane endpoint, while all isotype treated mice showed complete recovery from infection." (PMID 28953978, 2017). "The proinflammatory cytokines, such as IL-1β and IL-6, play essential roles on the initiation and propagation of inflammatory response, whose level in upper genital tract were increased with the pathogen infection and the recognition of immunogens by local TLRs." (PMID 27887650, 2016). "However, there were marked increases in the expression of IL-1β and IL-6 post-infection with CK/SD/w3 at 12 hpi (P > 0.05) and 18 hpi (P < 0.05), respectively, reaching the highest expression at 24 hpi (IL-1β at 19-fold and IL-6 at 21-fold, P < 0.01)." (PMID 27446066, 2016). "However, it is so far unclear whether the induction of IL-10 or IL-6 could directly increase cellular viral replication or whether they are only the byproducts of DENV-ADE infection." (PMID 26923481, 2016). "We speculate that CNS infection/inflammation can also increase CSF IL-10, a well-known inhibitory cytokine, which presumably results from immune cell secretion as a feedback response to pro-inflammatory cytokines, including IL-6, in the presence of infection/inflammation." (PMID 27924864, 2016). "In order to investigate if an infection with P. acnes type IA or II could modulate the secretion of pro-inflammatory mediators from prostate cells, the concentrations of IL6 and CXCL8 were measured in cell-media from cells infected with P. acnes and compared to uninfected cells." (PMID 27284286, 2016).
infection (continued). "In this study, significant increase in the levels of pro-inflammatory type 1 (TNF-α, IFN-γ, IL-6, IL-1β), pro-inflammatory type 2 (IL-33) and anti-inflammatory type 2 cytokines was observed in unimmunized mice after bacterial challenge indicating the spread of infection." (PMID 26904021, 2016). "Therefore, downstream of IFN-γ, both IL-27 and IL-6 may be necessary to induce the maximum myelopoiesis to control infection." (PMID 26991425, 2016). "For example, infection could induce the production of G-CSF/IL-6 and PGE2." (PMID 27270316, 2016). "Similarly, Chen and colleagues demonstrated that JEV disrupted the BBB, partially via the infection and activation of pericytes, which secreted IL-6 and induced the activation of the ubiquitin proteasome system and the subsequent degradation of the protein ZO-1." (PMID 27336851, 2016). "Our findings of higher IL-8, IL-6, and G-CSF among neutropenic subjects are consistent with the current knowledge of regulated neutrophil homeostasis, and suggest that the elevations represent a physiologic state whereby tissues are signaling for neutrophil recruitment to fight infection." (PMID 27431667, 2016). "However, because some cytokines such as IL-1β, IL-6, or IL-10 typically produced during infection are known to alter DC differentiation, indirect mechanisms might be of similar importance." (PMID 26870700, 2016). "Stimulation of TLR by bacterial recognition activated cytokine cascades such as IL-6 and IL-10 signaling pathways predominantly at 1 and 2 dpi, which lead to recruitment of other immune cells (e.g., neutrophils, dendritic cells) to the infection site in order to clear infection." (PMID 26738723, 2016). "During the infection process of invasive S. aureus, pathogen-associated-molecules initiate the innate immune system leading to activation and recruitment of neutrophils and macrophages and the production of pro-inflammatory cytokines, most notably TNF-α, IL-1β, and IL-6." (PMID 27917374, 2016). "To be able to test whether the IE1-STAT3 interaction diverts IL6 signaling also in the context of infection, we derived a mutant virus (TBIE1dl410-420) specifically lacking the sequence encoding IE1 amino acids 410 to 420 from a bacterial artificial chromosome (BAC) clone of the hCMV TB40/E strain." (PMID 27387064, 2016). "STAT3 activation in response to incubation with IL-6 was also suppressed by T3 in macrophages, indicating that inhibition of IL-6 signalling by the thyroid hormones also occurs in these cells that have potent regulatory functions during infection and inflammation." (PMID 27484112, 2016). "Interestingly, EAEC and mainly ETEC induced the highest levels of IL-6 at 4 h post-infection." (PMID 27774437, 2016). "Thus, the strong association of IL-6 with disease severity and death might be explained in two steps: firstly, through the inhibition of TNF-α in the early phase of infection, and later, by its inhibitory effect on Th1 responses." (PMID 26814478, 2016). "We also observed reduced secretion of interleukin-6 (IL-6, a pro-inflammatory cytokine) upon in vivo infection with the ΔelrA mutant strain and we hypothesized that ElrA may be involved in this modulation, by stimulating host immune cells to counteract E. faecalis infection." (PMID 26003173, 2015). "Early during infection (day 7, 1-2% parasitaemia), spleens showed disruption of germinal centre architecture with heavy B-cell activation (centroblasts), and splenocytes showed increased expression of IFNγ, IL6 and IL12 upon in vitro stimuli by P. falciparum-parasitized red blood cells (pRBC)." (PMID 25890318, 2015). "Furthermore, CRP is produced and secreted by signaling hepatocytes in response to proinflammatory cytokines such as IL-1β and IL-6 and the lag time from the onset of infection until CRP elevation is 6 to 8 hours, possibly interfering with the usefulness of this measurement." (PMID 25667565, 2015).
infection (continued). "The cytokines IL-6 and IL-8 are mediators of inflammation in response to bacterial infection, and when measured in plasma or serum these may be used as early biomarkers of infection." (PMID 25807366, 2015). "Our finding that IL-6 is expressed in the decidua of idiopathic spontaneous preterm labor is consistent with these observations and indicates that regardless of the presence of infection or gestational age, upregulation of IL-6 in gestational tissue is associated with spontaneous labor." (PMID 25961579, 2015). "Our finding that HBV Pol dramatically reduced IL-6 and IL-8 levels by interfering with the NF-κB signaling pathway may partially explain why the virus induces little detectable innate immune responses during early infection." (PMID 24618592, 2014). "Therefore, we combined those subjects with H. pylori infection and those without infection in the analysis on the association between serum IL-6 and iron levels." (PMID 24576354, 2014). "IL-6 and IL-8 production was predominant in microglial cells and neurons compared to endothelial cells, especially at 24 h post infection, which might suggest that these two interleukins have a role in controlling proliferation of RH and PRU strains in microglial cells and neurons." (PMID 24886982, 2014). "Finally, a study looking at the mechanisms by which blood-stage malaria infection can prevent the establishment of a liver-stage infection, which is thought to be modulated by hepcidin, found that liver-stage inhibition was preserved in mice treated with anti-IL-6 antibodies." (PMID 24910614, 2014). "Since the elevated levels of systemic proinflammatory cytokines (MCP-1, IL-1β, and IL-6) and increased peripheral blood leukocyte counts have been reported in obese humans and CPEfat/fat mice, we assessed these cytokines in serum and peripheral blood leukocyte counts after infection." (PMID 25203099, 2014). "Although we found no compensatory upregulation of either of these factors in IL-6-deficient mice by quantitative PCR, it is likely that infection stimulates other factors that may, for example, activate STAT3 through the relatively promiscuous IL-6/IL-12 family of ligands." (PMID 24185641, 2014). "Furthermore, the antibody array was randomly confirmed by qRT-PCR, and the results showed that pro-inflammatory chemokines including CCL5 and CCL2 and cytokines including IL-6, IL-1β, IL-12, and IL-17 were significantly enhanced after infection with aG and CTN." (PMID 25182681, 2014). "Interestingly, TLR2 priming resulted in diminished IL-6 mRNA following infection." (PMID 23853595, 2013). "Interestingly, while IL-6 has recently also been shown to be essential for viral control by enhancing follicular T helper cell responses at late stages of chronic infection, virus titers and Treg numbers were comparable in LCMV-DOC infected IL-6−/− and WT mice up to day 30 post infection." (PMID 23696736, 2013). "Thus, infection of osteoblasts by CHIKV and the consequent IL-6 production may contribute to bone loss and to the occurrence of arthralgia and arthritis." (PMID 24069610, 2013). "Importantly, most of the Mtb-infection induced IL-1β, IL-6, TNF-α and MCP-1 network genes were down regulated by PZA-treatment at both 42 and 63 days, while only 8–10% of these pro-inflammatory network genes were up-regulated, in all the four pro-inflammatory networks at both time points." (PMID 24015316, 2013). "In the present study, we genotyped SNPs of TNF, IFNG, IL6, IL10, and TGFB1 which are multifunctional cytokine that have been implicated in inflammation, immunity, and cellular organization and have been proposed to play important roles in infection and cancer biology." (PMID 23936772, 2013). "However, anti-IL-6 treatment at the time of infection is detrimental to the mice." (PMID 22956971, 2012).
infection (continued). "Since infection is also a potent inflammatory stimulus, a secondary, retrospective analysis was undertaken to examine the extent to which peripheral infection or ventriculostomy-related infection (VRI) was associated with observed changes in peripheral or central IL-6." (PMID 23176037, 2012). "Specifically, IL-1β and TNF-α signalling are negatively regulated by IL-6 and may compensate for the loss of IL-6, which could explain why IL-6−/− mice were not protected during H1N1pdm infection." (PMID 22679491, 2012). "However, infection of IL-6−/− mice resulted in disease indistinguishable from that in IL-6 wild-type mice, as measured by survival, weight loss, viral load, and pathology." (PMID 22679491, 2012). "Therefore, expression of IL-6 may be upregulated in response to bacteria as a protective mechanism to inhibit infection of the cells." (PMID 22642871, 2012). "Hence, the genes Ccl2, Ch25 h, Ifit3, Il1rn, Il6, Parp14, Ptx3, and Socs3 can be defined as a common core of genes expressed early in response to local infection and inflammation caused by Gram-negative stimuli." (PMID 21338499, 2011). "Thus the immunosuppressive environment created by IL-10 in synergism with IL-6 may lead to the virus persistence or secondary infection, which may result in the more severe symptoms in the severe P(H1N1) patients." (PMID 22174866, 2011). "Subsequently, however, there was a 15-25-fold induction of IL-6 gene expression in response to WT infection, while the response to ΔPT was reduced to near background levels, indicating that PT may be responsible for IL-6 induction subsequent to the early inhibition." (PMID 19759900, 2009). "We assessed whether IL-6 is produced following infection of mice with influenza virus." (PMID 18389078, 2008). "The pro-inflammatory cytokines IL-1β, TNF-α and IL-6, which are readily induced by the presence of lipopolysaccharides from Gram-negative bacteria play an important role in the synthesis of acute phase proteins and often participate in the pathogenesis of many infections." (PMID 18700003, 2008). "Interestingly, the determination of IL-6 levels in plasma 8 h after infection revealed that the ablation of mDCs in CD11cDTR/GFP transgenic mice affected only moderately the induction of IL-6, confirming that non-DCs contribute significantly to the Ad-elicited IL-6 response in vivo." (PMID 19008951, 2008). "NNIS, albumin, CRP and IL-6 may be useful as predictive markers for postoperative infections." (PMID 17505683, 2007). "In recent years, other parameters, such as interleukin-6 (IL-6) and procalcitonin (PCT), have attracted increasing interest as markers of infection." (PMID 41334533, 2026). "Upon pathogen encounter, macrophages secrete cytokines such as IL-6, IL-8, TNF, and C-C motif chemokine ligands (CCLs) to recruit monocytes to sites of infection, an essential process for effective host defense and maintenance of immune homeostasis." (PMID 41576161, 2026). "Early infection was marked by elevated lung CD4+ T cells (Th17/Treg), diminished Th1 cells and neutrophils, and increased blood cytokines (IFN-γ, IL-21, IL-6, IL-27)." (PMID 42112327, 2026). "IL-17 stimulates the production of other pro-inflammatory cytokines, such as IL-6, IL-1β, and TNF-α, and induces the production of chemokines that recruit neutrophils to the site of infection, amplifying the inflammatory response." (PMID 40145967, 2026). "During early kidney injury, M1 macrophages, induced by IFN‐γ and pro‐inflammatory signals, highly express iNOS and CD86, releasing IL‐1β, IL‐6, and TNF‐α to combat infection." (PMID 41527491, 2026). "In 70% of BEAS‐2B cultures with repeated infections (NOI 3–5, RV16), IL‐6 release led to an IL6TS high profile." (PMID 41099307, 2026). "The cytokine storm refers to the excessive activation of the immune system following infection, resulting in the massive release of various inflammatory cytokines, such as tumor necrosis factor‐alpha (TNF‐α), interleukin (IL)‐1β, and IL‐6." (PMID 41551210, 2026).